HR (HR lysine demethylase and nuclear receptor corepressor)
Diseases named in the same sentence as HR in open-access papers (continued):
Sharing a sentence is not in itself a finding about the gene and the disease.
breast cancer (continued). "In a cohort of patients diagnosed with HR+, HER2− advanced breast cancer, characterized by either de novo metastatic disease or late recurrence following neoadjuvant therapy, the frontline combination of ribociclib and letrozole significantly prolonged the OS over letrozole alone." (PMID 38339303, 2024). "HR+/HER2- breast cancer, typified by the expression of estrogen and/or progesterone receptors and the lack of HER2 gene amplification, constitutes approximately 65–70% of all breast cancer cases." (PMID 38605321, 2024). "From the NCDB cohort, we identified 53,346 patients with HR + /HER2- Stage I-III breast cancer with three or fewer lymph nodes involved and no missing data for candidate features." (PMID 38879577, 2024). "Breast cancer is the most common cancer among women in the United States, and hormone receptor-positive (HR+), human epidermal growth factor receptor 2 negative (HER2−) is the most common subtype." (PMID 39742366, 2024). "To further affirm this observation, we extended our investigation to a broader context by examining the expression patterns of LINC00960 across diverse breast cancer subtypes within the TCGA BRCA dataset, encompassing TNBC (n = 88), HER2+ (n = 33), HR+ (n = 351), and HR + HER2+ (n = 99) cases." (PMID 39039064, 2024). "The monarchE committee reported that among patients with early-stage HR+, HER2− breast cancer, and nodal involvement, the addition of abemaciclib to hormone therapy significantly improves cancer-specific free survival and decreases the risk of disease recurrence." (PMID 38218973, 2024). "Triple-negative breast cancer (TNBC) is the most aggressive subtype of breast cancer (BC), classically defined by the lack of expression of hormone receptors (HR, estrogen and progesterone receptors) and human epidermal growth factor receptor 2 (HER2)." (PMID 39478150, 2024). "A global Phase 3 clinical trial (VIKTORIA‐1, NCT05501886) is currently evaluating gedatolisib in combination with fulvestrant, with and without palbociclib, in patients with HR+/HER2− advanced breast cancer." (PMID 39092562, 2024). "The Prosigna Breast Cancer Assay is intended for monitoring breast cancer patients within a specific group of post-menopausal women, whose stage does not exceed 3 and are HR+/HER2−." (PMID 39185467, 2024). "Immunotherapy has shown progress in treating triple-negative breast cancer, but immunological research on HR+/HER2– breast cancer is still in its early stages." (PMID 39531335, 2024). "About 70% of newly diagnosed breast cancers belong to a specific subgroup called hormone receptor positive (HR+)/Human epidermal growth factor receptor 2 negative (HER2-)." (PMID 38817360, 2024). "Despite significant progress with CDK4/6 inhibitors, no phase 3 studies have evaluated the efficacy and safety of palbociclib in combination with tamoxifen in patients with HR+/HER2− advanced breast cancer regardless of menopausal status." (PMID 39174547, 2024). "Currently, elderly patients with HR+/HER2+ breast cancer are most frequently treated with ET alone, without anti-HER2 therapy." (PMID 39766087, 2024). "This study included patients in Japan with HR+, HER2− breast cancer across a wide age range." (PMID 36414795, 2023). "Implementation of CDK4/6 inhibitors (CDK4/6i) into clinical routine has revolutionized the treatment of patients with hormone receptor positive, HER2 negative advanced breast cancer (HR+/HER2− ABC)." (PMID 36876172, 2023). "This study extends our understanding of real-world CDK4 and 6 inhibitor use in Japan, providing insight into current treatment practices for HR+, HER2− advanced breast cancer, specifically in relation to treatment patterns of CDK4 and 6 inhibitor use and their clinical outcomes." (PMID 36414795, 2023).
breast cancer (continued). "The analysis also revealed a similar ADAM8 positivity rate (~ 30%) in all other non-TNBC breast cancer subtypes, including HR−/HER2+ (6/22 = 27.3%), HR+/HER2− (100/301 = 33.2%) and HR+/HER2+ (9/28 = 32.1%), that had not been examined previously." (PMID 37568162, 2023). "CDK4/6 inhibitors (CDK4/6i) combined with endocrine therapy are considered standard-of-care for first-line therapy of patients with hormone receptor positive, HER2 negative, advanced breast cancer (HR+/HER2− ABC)." (PMID 36876172, 2023). "However, the tumor immune microenvironment (TME) in different subtypes of breast cancers, like TNBC, hormone receptor‐positive (HR+), and human epidermal growth factor receptor 2 amplified (HER2+) and its changes by NAT remain to be fully characterized." (PMID 36073303, 2022). "Breast cancer is further divided into three major subtypes: hormone receptor positive/HER2 negative (HR+/HER2−), HER positive (HER2+), and triple-negative." (PMID 36248976, 2022). "Therefore, predictive or prognostic multigene assays should be more applied in clinic practice in patients with HR+/HER2‐, early‐stage breast cancer." (PMID 34390318, 2022). "The most common subtype of breast cancer in AA, Arab, Hispanic, and NHW groups was HR + although HER2 status was unknown in 16.3% of cases." (PMID 35040284, 2022). "In addition, 69.0% (180/261, 95%CI: 63.0%–74.5%) modified N0 and 98.1% (203/207, 95%CI: 95.1%–99.5%) modified N1 patients with HR+/HER2‐, early‐stage breast cancer received chemotherapy." (PMID 34390318, 2022). "The method was successfully applied to samples from patients treated for HR+, HER2− breast cancer." (PMID 35631440, 2022). "Breast cancer is one of the highest rates of malignancy of women, approximate 70% metastatic breast cancer are hormone receptor positive (HR+) and human epidermal growth factor receptor 2 negative (HER2−)." (PMID 36595763, 2022). "Hormone receptor positive (HR+)/human epidermal growth factor receptor 2 negative (HER2−) BC accounts for approximately two-thirds of all breast cancers and as a result, hormone therapy plays an integral role in breast cancer patients." (PMID 36595763, 2022). "The genomic tests such as the MammaPrint and Oncotype DX test are being gradually applied for hormone receptor positive/HER-2 negative (HR+/HER2-) breast cancer patients with up to three positive axillary lymph nodes (ALNs)." (PMID 34422668, 2021). "CompLEEment-1 is a phase 3b trial in an expanded patient population with hormone receptor-positive (HR +), human epidermal growth factor receptor-2–negative (HER2–) advanced breast cancer (ABC), the largest current trial of cyclin-dependent kinase 4 and 6 inhibitors in ABC." (PMID 34414532, 2021). "Breast cancer is the most common cancer in women, and approximately 71% of carcinomas are hormone receptor‐positive (HR+) and human epidermal growth factor receptor 2‐not‐amplified (HER2‐negative)." (PMID 32697890, 2020). "Data were from phase 3, randomized PALOMA-2 and PALOMA-3 clinical studies of hormone receptor‒positive/human epidermal growth factor receptor 2‒negative (HR+ /HER2−) advanced breast cancer (ABC) patients receiving endocrine therapy plus palbociclib or placebo." (PMID 32783178, 2020). "This cohort includes patients with HR+, HER2-amplified, and TNBC breast cancer subtypes." (PMID 33298946, 2020). "We identified KMT2C p.K2797fs as a frequently mutated mutation in Chinese breast cancer but not in the MSKCC cohort (2% versus 0%, FDR < 0.05), and this finding was particularly true in the HR+/HER2− subtype (top left)." (PMID 33173047, 2020). "Notably, compared with the TCGA and MSKCC cohorts, patients with HR−/HER2+, HR+/HER2+, and HR−/HER2− breast cancers were more predominant in our study cohort." (PMID 33173047, 2020).
breast cancer (continued). "The final PFS data confirmed that abemaciclib dosed on a continuous schedule in combination with a nonsteroidal AI provided statistically significant increases in median PFS and ORR as an initial treatment for postmenopausal women with HR+, HER2− advanced breast cancer." (PMID 30675515, 2019). "The content validity of both the NFBSI-16 and PROMIS Physical Function Short Form 10b has been evaluated previously in breast cancer and cancer populations more generally, but not in an HR+/HER2- advanced breast cancer population specifically." (PMID 31142325, 2019). "Breast tumors that are HR+ and/or HER2+ account for 80–85% of breast cancer cases." (PMID 30813596, 2019). "In a reported phase II study, two (5%) of the 37 enrolled patients had HR+/HER2+ breast cancer, without prior HER2-directed treatment." (PMID 31777590, 2019). "At the preplanned interim analysis of the MONARCH 3 trial, abemaciclib in combination with a nonsteroidal AI demonstrated significant improvements in PFS and ORR with a generally tolerable safety profile as initial therapy for patients with HR+, HER2− advanced breast cancer." (PMID 30675515, 2019). "Over two-thirds of patients diagnosed with HR+, HER2− breast cancer are aged 65 years or older." (PMID 29058175, 2018). "In this randomized, placebo-controlled phase II trial, we evaluated whether the addition of dovitinib to fulvestrant would improve outcomes in postmenopausal patients with HR+, HER2− advanced breast cancer that had progressed during or after prior ET." (PMID 28183331, 2017). "In this randomized, double-blind trial, we evaluated the safety and efficacy of dovitinib plus fulvestrant compared with placebo plus fulvestrant in postmenopausal patients with HR+, HER2− advanced breast cancer that progressed during or after prior endocrine therapy." (PMID 28183331, 2017). "Inhibitors against cyclin-dependent kinase 4/6 (CDK4/6) are an important new class of agents with substantial antitumor activity in patients with advanced hormone receptor-positive (HR+) and human epidermal growth factor receptor 2-negative (HER2−) breast cancer." (PMID 29162134, 2017). "Breast cancer, a heterogeneous disease composed of distinct biological subtypes, can be divided into four simple subtypes based on ER, PR and HER2 status: hormone receptor (HR)+/HER2−, HR+/HER2+, HR−/HER+, and HR−/HER2−." (PMID 27322074, 2016). "Breast cancer can be classified into several subtypes based on the expression of hormone receptors [HR, including estrogen receptor (ER) and progesterone receptor], human epidermal growth factor receptor 2 (HER2), and Ki67: HR-positive, HER2-positive, and triple-negative breast cancer (TNBC)." (PMID 40949156, 2025). "While there is clinical benefit for combined anti-PD-1 blockade and chemotherapy for a subset of patients with early stage and metastatic triple negative breast cancer, no such gains have been observed for most patients with HR+/HER2-negative breast cancer, particularly in the metastatic setting." (PMID 38502947, 2024). "On the one hand, unlike other subtypes of breast cancer, HR+/HER2+ breast cancer is endowed with distinct molecular biological characteristics, therapeutic responses and drug resistance mechanisms due to the complex interaction between HR and the HER2 signaling pathway." (PMID 38185807, 2024). "The addition of cyclin-dependent kinases inhibitors (CDKi) to endocrine therapy (ET) as the first- or second line treatment improves progression-free and overall survival (OS) in hormone receptor-positive, HER2 negative (HR+/HER2-) advanced stage breast cancer (ABC)." (PMID 38414945, 2023). "Breast cancers that express the hormone receptors (HRs) Estrogen Receptor-α (ER) and Progesterone Receptor (PR), but not Human Epidermal Growth Factor Receptor-2 (HER2) [HR+/HER2−] are the most common subtype (68%), followed by HR+/HER2+ and HR−/HER2− (10% each) and HR−/HER2+ (4%) [NCI]." (PMID 37568162, 2023).
breast cancer (continued). "Our study evaluated the renal safety of abemaciclib plus endocrine therapy (ET) with bisphosphonate as a treatment option for hormone receptor positive, human epidermal growth factor receptor 2 (HER‐2) negative (HR+/HER2−) advanced breast cancer (ABC), especially with bone metastasis." (PMID 36351632, 2023). "Roughly 70% to 75% of all breast cancers are both HR+ and HER2 negative (HER2-)." (PMID 36515302, 2022). "Therefore, the aim of this study was to describe temporal trends and examine rural-urban differences in GEP testing among women diagnosed with early-stage, HR+, HER2−, and LN− breast cancer in Iowa and among women who received ODX, determining how the results are associated with chemotherapy use." (PMID 36111211, 2022). "Indeed, PIGNON identifies dysregulated functional annotations in the hormone receptor positive (HR+), human epidermal growth factor receptor 2 (HER2+) and triple negative (TN) breast cancer subtypes, providing insights into the molecular mechanisms of these conditions." (PMID 34088263, 2021). "In the current study, we focused on luminal-like breast cancer comprising the luminal-A and luminal-B subtypes, which are defined by the presence of hormonal receptor and absence of HER2 on the plasma membrane of tumor cells (i.e., HR+/HER2-) by the immunohistochemistry." (PMID 29796180, 2018). "Notably, patients with HR+/HER2- and HER2+ breast cancer subtypes were more likely to remain on their systemic therapy following MDRT, although whether this is due to inherit differences in prognosis or the effect of MDRT remains uncertain due to the lack of a control group." (PMID 40647452, 2025). "A total of 301 Chinese patients with different BC subtypes including 47 HR+/HER2+, 185 HR+/HER2−, 38 HR−/HER2+, and 31 triple‐negative breast cancer (TNBC) were enrolled in our study." (PMID 36404592, 2023). "However, most of our patients with HR+/HER2‐, early‐stage breast cancer (69.0% N0 and 98.1% N1) had received chemotherapy in this study, which may due to the inadequate application of Oncotype Dx, EndoPredict, Mammaprint and other gene expression assays in real‐world practice of southern China." (PMID 34390318, 2022). "The sensitivities of diagnosing human epidermal growth factor receptor 2 ‐positive (HER2+) breast cancer and triple‐negative breast cancer (TNBC) were 100%, and for the hormone receptor‐positive (HR+)/HER2‐negative (HER2−) subtype, they were 93.1%." (PMID 40539820, 2025). "We retrospectively analyzed 66 patients with HR+/HER2-, node-negative early breast cancer treated between 2023 and 2024." (PMID 40416209, 2025). "The recent development of cyclin-dependent kinase 4/6 (CDK4/6) inhibitors, such as ribociclib, has considerably improved the management of hormone receptor positive (HR+) and HER2 negative (HER2-) advanced breast cancer." (PMID 38046373, 2023). "This extensive sample collection allowed us to examine ADAM8 expression for the first time in breast cancer subtypes beyond TNBC (HR−/HER2−), including HR−/HER2+, HR+/HER2− and HR+/HER2+, that we had never examined previously." (PMID 37568162, 2023). "The analysis revealed a similar positivity rate (~ 30%) in the non-TNBC breast cancer subtypes, including HR+/HER2−, HR−/HER2+, and HR+/HER2+ that had not been examined previously." (PMID 37568162, 2023). "For the first time, these non-TNBC breast cancer samples were similarly found positive for ADAM8: 27.3%, 33.2% and 32.1% for HR−/HER2+, HR+/HER2− and HR+/HER2+ patient samples, respectively." (PMID 37568162, 2023). "Real-world Ki-67 testing use is not well characterized among patients with HR+, HER2− early-stage breast cancer." (PMID 35524219, 2022). "In line with this, our study suggests that Ki-67 testing is not widely used in US patients with HR+, HER2− breast cancer, with less than a quarter (22.9%) of the patient population tested." (PMID 35524219, 2022).
breast cancer (continued). "It is also noted that most of the patients with HR+/HER2‐, early‐stage breast cancer were treated with aggressive chemotherapy without knowing the risk of chemotherapy induced lymphopenia." (PMID 34390318, 2022). "Hormone receptor-positive (HR+) and human epidermal growth factor receptor 2 negative (HER2−) breast cancer are the most common subtypes, accounting for approximately 70% of all breast cancer cases in the United States." (PMID 36111211, 2022). "The results from this study show that Ki-67 testing is not widely used in US patients with HR+, HER2− early breast cancer." (PMID 35524219, 2022). "In line with NCCN Guidelines, HR+, HER2− early breast cancers were mostly treated with ET with or without CT." (PMID 35524219, 2022). "As reported in literature, HR+, HER2-, with low ki67, breast cancer have not been completely satisfactory response rates to standard neoadjuvant chemotherapy." (PMID 35223478, 2022). "Endocrine therapy (ET) forms the foundation of treatment for hormone receptor positive (HR+), human epidermal growth factor receptor 2 negative (HER2-) advanced breast cancer." (PMID 35223458, 2021). "In recent years, cyclin-dependent kinase 4 and 6 inhibitors (CDK4/6i), including palbociclib, ribociclib, and abemaciclib, have been approved for the treatment of hormone receptor-positive (HR+), human epidermal growth factor receptor-negative (HER2-) advanced breast cancer (ABC)." (PMID 39935426, 2025). "In recent years, multigene tests such as Oncotype DX, MammaPrint, Breast Cancer Index, Prosigna (PAM50), and EndoPredict have transformed the management of hormone-receptor positive (HR+)/human epidermal growth factor-receptor 2 negative (HER2–) early breast cancer (BC)." (PMID 40717834, 2025). "Breast cancer includes four widely recognized subtypes: luminal A (hormone receptor positive/human epidermal growth factor receptor 2 negative, HR+/HER2−), luminal B (HR+/HER2+), HR−/HER2+, and triple negative (HR−/HER2−)." (PMID 37623478, 2023). "Most HR+, HER2− early breast cancers were treated with adjuvant ET, with or without CT." (PMID 35524219, 2022). "The recent addition of cyclin-dependent kinase 4 (CDK4) and CDK6 inhibitors to endocrine therapy has remarkably improved the outcome of patients affected with hormone receptor positive (HR+), human epidermal grow factor receptor 2 negative (HER2 -) advanced breast cancer (ABC)." (PMID 35223478, 2022). "This includes a global phase Ib study of CYH33 in combination with olaparib in advanced solid tumors (NCT04586335) and a phase Ib study of CYH33 in combination with endocrine therapy with or without palbociclib in patients with HR+, HER2− advanced breast cancer (NCT04856371)." (PMID 36385120, 2022). "Molecular factors that drive metastasis in premenopausal patients with hormone receptor positive (HR+), human epidermal growth factor receptor 2 negative (HER2−), early breast cancer (EBC) are largely unknown." (PMID 34575612, 2021). "We also investigated the prognostic impact of the immune-related markers across the 3 breast cancer subtypes: hormone receptor negative/HER2− (TN), hormone receptor positive/HER2− (HR+), and hormone receptor positive or hormone receptor negative/ HER2+ (HER2+)." (PMID 30285668, 2018). "Therefore, unlike the other subtypes of breast cancer, pCR after NET may not be as good a surrogate endpoint for long-term outcomes in patients with HR+, HER2− patients, even in those with cN+ disease." (PMID 39742366, 2024). "In different subtype of breast cancer, the median PFS was 5.6 months, 5.7months, and 6.4 months in human epidermal growth factor receptor 2 positive (HER2+), hormone receptor positive and HER2 negative (HR+/HER2-), and triple negative breast cancer (TNBC) patients, respectively." (PMID 36568219, 2022).